PIM2 (Pim-2 proto-oncogene, serine/threonine kinase)
Diseases named in the same sentence as PIM2 in open-access papers (continued):
Sharing a sentence is not in itself a finding about the gene and the disease.
breast cancer (continued). "Interestingly, PIM2 expression is positively correlated with tumor stage and size in breast cancer, and knockdown of PIM2 increases TTP protein levels in vivo, which promotes breast tumor growth." (PMID 29570932, 2018). "Our results suggest that the PIM2 is a potential therapy target for the treatment of breast cancer." (PMID 29570932, 2018). "Our data further suggested that the PIM2-mediated HK2 phosphorylation may provide a potential therapeutic target for the treatment of breast cancer." (PMID 29985480, 2018). "However, the mechanisms by which PIM2 regulates breast cancer remain uncharacterized." (PMID 29570932, 2018). "For example, PIM2 mediates phosphorylation and stabilization of PFKFB3, leading to enhanced glycolysis and paclitaxel resistance in breast cancer cells." (PMID 37444501, 2023). "PIM2 and STAT3 form a positive feedback loop that regulates epithelial-to-mesenchymal transition in breast cancer." (PMID 34511042, 2021). "Lastly, breast cancer tissues exhibited higher PIM2 and FBP1 Ser144 phosphorylation expression than normal, tumor-adjacent breast tissues, suggesting its importance for breast cancer progression." (PMID 32754266, 2020). "Obviously, immunohistochemical staining revealed that PIM2 and pT473-HK2 were strongly expressed in breast cancer tissues but had reduced expression in normal breast tissues." (PMID 29985480, 2018). "To determine the expressions levels of PIM2 and pT473-HK2 in breast cancer tissues, we performed immunohistochemistry assays in 10 cases of normal breast tissues and 46 cases of breast cancer tissues." (PMID 29985480, 2018). "Our results demonstrated that PIM2‐mediated TTP degradation was crucially involved in the regulation of proliferation and migration in breast cancer cells." (PMID 29570932, 2018). "Taken together, our findings indicated that PIM2 was a novel regulator of HK2, and suggested a new strategy to treat breast cancer." (PMID 29985480, 2018). "To investigate if PIM2 and HK2 conferred paclitaxel resistance in breast cancer cells, we analyzed the effects of PIM2 and HK2 knockdown on the cell proliferation rates of MCF-7/TaxR cells following paclitaxel treatment." (PMID 29985480, 2018). "Here, we discovered a novel interaction between PIM2 and HK2 proteins, both of which were upregulated and correlated with each other in human breast cancer tissues." (PMID 29985480, 2018). "To determine the expressions of PIM2 and TTP in breast cancer tissues, we performed immunohistochemistry (IHC) assays in 84 cases of breast cancer tissues, and 10 cases of normal breast tissues as control." (PMID 29570932, 2018). "Nevertheless, the phosphorylation at another amino acid residue, Thr120, by PIM2 protects it from being degrading by FBXW7 and results in the accumulation of HSF1, which subsequently induces the expression of PD-L1 in breast cancer and enhances growth of breast cancer." (PMID 35814468, 2022). "PIM2-mediated phosphorylation of HSF1 at Thr-120 also induces HSF1 binding to the PD-L1 promoter and enhances PD-L1 expression, which also promotes tumor growth in breast cancer." (PMID 33854618, 2021). "We demonstrates that PIM2 mediates PFKFB3 phosphorylation thus regulates glycolysis and paclitaxel resistance to promote tumor progression in breast cancer, and provides preclinical evidence for targeting PFKFB3 as a new strategy in breast cancer treatment to battle paclitaxel resistance." (PMID 33931981, 2021). "Moreover, the levels of PIM2 and pSer144-FBP1 proteins were positively correlated with each other in human breast cancer and PIM2 knockout mice." (PMID 32754266, 2020). "As a result, PIM2 stimulates TTP‐mediated proliferation and migration in breast cancer cells." (PMID 29570932, 2018).
breast cancer (continued). "Biochemical analyses demonstrated that phosphorylated HK2 Thr473 promoted its protein stability through the chaperone-mediated autophagy (CMA) pathway, and the levels of PIM2 and pThr473-HK2 proteins were positively correlated with each other in human breast cancer." (PMID 29985480, 2018). "Furthermore, immunohistochemical staining showed that PIM2 and TTP protein levels were negatively correlated in human breast cancer samples." (PMID 29570932, 2018). "Moreover, the expression levels of PIM2 and pThr473-HK2 were positively correlated in breast cancer tissues." (PMID 29985480, 2018). "Immunohistochemical staining revealed that PIM2 was strongly expressed in breast cancer tissues; TTP, however, was expressed more in normal breast tissues." (PMID 29570932, 2018). "We also determined the correlation between PIM2 and TTP expression in breast cancer." (PMID 29570932, 2018). "Importantly, we report that small molecule inhibition of two of these genes, PIM2 and ZAK, is synergistic with PI3K inhibition, a finding that has therapeutic implications for the treatment of breast cancer." (PMID 28561737, 2017). "Our findings further suggest that PIM2-mediated non-canonical FBP1 phosphorylation may be targeted in breast cancer therapies." (PMID 32754266, 2020).
leukemia (17 papers, 2009 to 2026). A malignant (clonal) hematologic disorder, involving hematopoietic stem cells and characterized by the presence of primitive or atypical myeloid or lymphoid cells in the bone marrow and the blood. "One example involved the oncogene PIM2, a gene typically associated with leukemias, for which SNVs across the region 20kb upstream of the gene associated with elevated expression in pediatric brain tumors." (PMID 33554123, 2021). "A recent report illustrated the capacity of 3L3-L1 preadipocytes to protect human leukemia cell lines from chemotherapeutic agents, an effect which was independent of cell contact and associated with the increased expression of antiapoptotic factors Pim-2 and Bcl-2." (PMID 32906729, 2020). "PIM2 is expressed in myeloma, lymphoma, and leukemia, whereas PIM1 is detected in many types of solid tumors and blood cancers." (PMID 38339286, 2024). "Pim-1 was highly expressed in complex AML, CLL, ALL, and MDS, while Pim-2 was especially prevalent in CML compared to other leukemias." (PMID 36694243, 2023). "PIM2 is largely expressed in both leukemia and solid tumors, and it promotes the transcriptional activation of genes involved in cell survival, cell proliferation, and cell-cycle progression." (PMID 33854618, 2021). "All the mice showed an AML-like phenotype, except the mice with PIM2 as a secondary proto-oncogene, which showed a pro-B-cell phenotype of leukemia as well." (PMID 26606454, 2015). "Similarly, PIM2 is overexpressed in both leukemia and solid tumors and stimulates the transcription of genes involved in cell survival, proliferation, and cell cycle progression." (PMID 38339286, 2024). "As part of our laboratory drug discovery program aimed at identifying new targeted therapies for the treatment of hematologic malignancies, and, regarding the particular potential of Pim-1 and Pim-2 as targets in leukemia, we decided to develop new dual Pim-1/Pim-2 specific inhibitors." (PMID 33562106, 2021). "Pim-2 was found to cooperate with PRα to induce APL in mice, possibly by enhancing the likelihood of clonal events that lead to leukemia." (PMID 36694243, 2023). "The appearance of PIM2 and MYC together in three different mice strongly suggests that the two proto-oncogenes synergistically stimulate leukemia development." (PMID 26606454, 2015).
prostate carcinoma (13 papers, 2011 to 2022). A carcinoma that arises from epithelial cells of the prostate gland. "PIM-1 and PIM-2 are implicated in prostate cancer development, PIM-1 is over expressed in head and neck squamous cell carcinoma and bladder cancer and PIM-3 is over expressed in colorectal, pancreatic and hepatocellular carcinoma." (PMID 22193779, 2011). "Pim-2 is a potent anti-apoptotic factor and its upregulation is associated with prostatic carcinoma tumorigenesis, suggesting that Pim-2 overexpression may cause direct eIF4B phosphorylation during PCa tumorigenesis." (PMID 30761182, 2019). "In addition, elevated levels of PIM-2 were associated with severe clinical and pathological symptoms in prostate cancer, and hence with poor prognosis." (PMID 22506047, 2012). "XIAP, a downstream factor in the PIM2 pathway in prostate cancer, has been shown to cooperate with PIM2 to inhibit apoptosis in prostate cancer cells." (PMID 33854618, 2021). "Numerous studies have shown the overexpression of PIM2 in many cancers, including BC, prostate cancer, endometrial cancer, lung cancer, and lymph cancer." (PMID 33931981, 2021). "PIM2 promotes apoptosis in HeLa cells, which is also observed in prostate cancer cells and colorectal cancer cells." (PMID 24505470, 2014). "PIM-1 and PIM-2 over expression in prostate cancer correlates with tumour progression and over expression of exogenous PIM-1 or PIM-2 in prostate cancer cell lines increases cell proliferation." (PMID 22193779, 2011). "PIM-2 inhibited apoptosis of prostate cancer cells by downstream factor XIAP." (PMID 32062612, 2020). "Moreover, increased expression of PIM-2 was directly associated with various malignancies, such as non-Hodgkin's lymphoma, CLL and prostate cancer, further supporting the oncogenic function ascribed to PIM-2, and justifying targeting its kinase activity as a beneficial therapeutic approach." (PMID 22506047, 2012). "BIRC3 and PIM2 are recognized anti-apoptotic factors, and GSTM2 is a biomarker for the early stages of the prostate cancer." (PMID 34209090, 2021). "A recent study suggested that PIM-2 cooperates with downstream factor XIAP, and thus inhibits the apoptosis of prostate cancer cells." (PMID 32062612, 2020). "PIM2 and runt-related transcription factor 1 (RUNX1) oncogenes have critical role in the development of several kinds of tumors, including prostatic carcinoma." (PMID 23023193, 2012).
acute myeloid leukemia (9 papers, 2012 to 2025). Acute myeloid leukemia (AML) is a group of neoplasms arising from precursor cells committed to the myeloid cell-line differentiation. "RSK2, a critical serine/threonine-protein kinase that acts downstream of ERK in FLT3-ITD-acute myeloid leukemia (AML), was also identified as another PIM2 target." (PMID 34770845, 2021). "Two of the 23 MM essential genes, PIM2 and IKBKB, are catalogued as targets for six therapies across 19 disease categories: nine in the context of cancer including MM, non-Hodgkin lymphoma, and acute myeloid leukaemia." (PMID 35882937, 2022). "Some of these genes have already been shown to play a role in hematologic malignancies, including CLL (Pim-2, Met, Rgs16, Ccdc88a, Zcchc18, Clip3), diffuse large B cell lymphoma, follicular lymphoma (Vav3), acute lymphoblastic leukemia (ALL) (Itm2a, Chst1) or acute myeloid leukemia (AML) (Chd3)." (PMID 30271400, 2018). "One of the most promising PIM inhibitors (PIMi) was SGI-1776, a compound with activity against PIM1, PIM2 and PIM3 at nanomolar concentrations, which induced apoptosis at micromolar doses in chronic lymphocytic leukemia, mantle cell lymphoma, and acute myeloid leukemia." (PMID 25386922, 2014). "Expression of both PIM1 and PIM2 are elevated in diffuse large B-cell lymphoma (DLBCL), while PIM2 alone is most highly expressed in B-cell chronic lymphocytic leukemia, acute myeloid leukemia (AML), and MM." (PMID 34503111, 2021).
hepatocellular carcinoma (8 papers, 2014 to 2025). A malignant tumor that arises from hepatocytes. "In hepatocellular carcinoma tissues, PIM2+ cells were enriched in regions containing high levels of macrophages and T cells." (PMID 36429128, 2022). "PIM2 promotes hepatocellular carcinoma tumorigenesis and progression through activation of the NF‐κB signaling pathway." (PMID 33931981, 2021). "MicroRNA-26b-5p was also found to have the ability to enhance T-cell responses by targeting Pim-2 in hepatocellular carcinoma." (PMID 34692670, 2021). "In addition, proinflammatory macrophages trigger PIM2 expression in hepatocellular carcinoma cells which acquire the capability to survive, metastasize, and resist T-cell cytotoxicity and immunotherapy." (PMID 40046063, 2025). "In hepatocellular carcinoma (HCC), the expression of PIM2 has been shown to be both significantly up-regulated and associated with poor patient prognoses." (PMID 33854618, 2021). "In hepatocellular carcinoma cells, hypoxia-inducible factor-1alpha (HIF-1α) and hypoxia-inducible factor-2alpha (HIF-2α) bind directly to the PIM2 promoter and induce PIM2 expression." (PMID 35892829, 2022).
gastric cancer (6 papers, 2020 to 2025). A primary or metastatic malignant neoplasm involving the stomach. "Proviral insertion in murine lymphomas 2 (PIM2) is reported to act as an oncogene in gastric cancer, controlling apoptosis via ROS-triggered ER stress, and promoting the development of gastric cancer." (PMID 37143652, 2023). "It have previously reported up-regulated PIM2 in human gastric cancer specimens, along with increased gastric cancer cell invasion and migration." (PMID 33854618, 2021). "PIM2 has been shown to promote stomach cancer progression by regulating apoptosis during reactive oxygen species-triggered endoplasmic reticulum stress." (PMID 33854618, 2021). "Six of them (β-catenin, C-MYC, CXCL13, DC-SIGN, EGFR, and PIM2) are consistently described as oncogenes according to the literature, and are overexpressed at the protein or mRNA level in gastric tissue among infected children and gastric cancer patients." (PMID 32117120, 2020).
B-cell lymphomas (5 papers, 2012 to 2015). "PIM2 is known to be associated with an aggressive clinical course in B-cell lymphomas, and is involved in the regulation of mTOR complex 1 (mTORC1)." (PMID 26340096, 2015). "Integration into the pim2 locus leads to enhanced mRNA production and promotes T- and B-cell lymphomas." (PMID 24860787, 2014). "A pool of important genes involved in B-cell development, oncogenesis, cell cycle regulation, and cell death including BATF, LIMD1, CFLAR, PIM2, and CCND2 are common signatures associated with IRF4 in non-Hodgkin B cell lymphomas." (PMID 25207815, 2014). "In Pim1-KO mice, integration of M-MulV into the pim2 locus, which occurs in 25% of all integrations, provokes T- and B-cell lymphoma via enhanced mRNA production." (PMID 24860787, 2014).
lung carcinoma (5 papers, 2020 to 2023). "The PIM2 encodes a protooncogene that acts as a serine/threonine protein kinase to promote cell survival and participate in the progress of lung cancer." (PMID 38071755, 2023). "We confirmed that SOX21-AS1 can interact with miR-24-3p through competitive endogenous RNA mechanism, thereby affecting the expression of PIM2 and relieving the lung cancer development." (PMID 34511042, 2021). "In conclusion, this study showed that SOX21-AS1 negatively modulated the miR-24-3p/PIM2 axis to potentiate the proliferation, migration, and invasion capabilities of lung cancer cells." (PMID 34511042, 2021). "Consistent with the results from previous studies, lung cancer tissues and cells were found to have relatively high expression levels of PIM2." (PMID 34511042, 2021). "Here, the levels of SOX21-AS1, miR-24-3p, and PIM2 were examined in lung cancer and normal tissues." (PMID 34511042, 2021). "PIM2, which showed elevated levels in lung cancer, was the target of miR-24-3p." (PMID 34511042, 2021). "We hypothesized that SOX21-AS1 regulates the growth and metastasis of lung cancer cells via miR-24-3p/PIM2 axis." (PMID 34511042, 2021). "The targeting of PIM2 by miR-24-3p disrupted the cellular activities of lung cancer cells." (PMID 34511042, 2021). "In lung cancer cells, SOX21-AS1 negatively modulated the miR-24-3p/PIM2 axis to facilitate their proliferation, migration, and invasion." (PMID 34511042, 2021). "PIM2 levels were markedly higher in lung cancer tissues than in non-tumor tissues." (PMID 34511042, 2021).
ovarian carcinoma (5 papers, 2017 to 2025). A malignant neoplasm originating from the surface ovarian epithelium. "PIM2 is also induced by cisplatin in ovarian cancer cells, and the targeting of the PIM2 kinase by biochemical inhibitors or RNA interference leads to the reduction of cell growth, the decrease of BAD phosphorylation, and the sensitization of the ovarian cancer cells to drug-induced apoptosis." (PMID 33854618, 2021). "In human breast, endometrial and ovarian cancer, a subset of tumors showed high levels of PIM1 and PIM2 correlating with inflammatory molecules." (PMID 28938604, 2017).
acute lymphoblastic leukemia (4 papers, 2018 to 2025). Leukemia with an acute onset, characterized by the presence of lymphoblasts in the bone marrow and the peripheral blood. "Moreover, previous study showed that adipocytes protected acute lymphoblastic leukaemia (ALL) cells from vincristine, a chemotherapeutic agent, by sequestering lipophilic vincristine, as well as upregulating anti-apoptotic proteins, Pim-2 and Bcl-2." (PMID 31334678, 2019). "Metformin, AMPK-dependently, blocked the activation of the UPR in acute lymphoblastic leukemia (ALL) cells and synergized with both AKT and the proviral insertion site in moloney murine leukemia virus (PIM-2) inhibitors." (PMID 33182253, 2020).
B-cell chronic lymphocytic leukemia (4 papers, 2014 to 2022). "PIM2 is a oncogene that have been validated in breast, liver cancer and chronic lymphocytic leukemia." (PMID 36105819, 2022).
breast tumors (4 papers, 2017 to 2020). "FBP1 phosphorylation by PIM2 promoted breast tumor growth and p65-induced PD-L1 expression, highlighting the role of PIM2-dependent FBP1 phosphorylation in breast tumor progression." (PMID 32754266, 2020). "Consistently, we found that PIM2 protein levels were positively correlated with tumor size and stage of breast tumors, whereas TTP protein levels were negatively correlated." (PMID 29570932, 2018). "To determine whether the PIM2‐mediated TTP regulates breast tumor growth in vivo, we performed xenograft studies." (PMID 29570932, 2018). "In addition, PIM2 regulated TTP‐reduced cell proliferation and migration, implying that the PIM2–TTP complex plays a significant role in the progression of human breast tumors." (PMID 29570932, 2018). "We found 665 genes which expression significantly correlated with the expression of PIM1 and PIM2 in human breast tumors (Pearson r > 0,3), 296 that significantly correlated to PIMs in endometrial tumors (Pearson r > 0,3) and 6661 in ovarian tumors (Pearson r > 0,3)." (PMID 28938604, 2017). "We analyzed PIM2 and FBP1 Ser144 phosphorylation expression levels by western blot in breast tumors (T) and their adjacent normal tissues (N)." (PMID 32754266, 2020).
endometrial cancer (4 papers, 2020 to 2022). Primary or metastatic malignant neoplasm involving the endometrium (mucous membrane that lines the endometrial cavity). "In endometrial cancer, the phosphorylation of AMPΚα1 on Thr-467 by PIM2 results in less AMPΚα1 kinase activity, which in turn promotes tumor growth." (PMID 33854618, 2021). "In endometrial cancer, PIM2 has been shown to inhibit AMPKα1 kinase activity through direct phosphorylation on Thr-467, leading to the decrease of AMPKα1 kinase activity and the promotion of aerobic glycolysis and tumor growth." (PMID 33854618, 2021).
liver cancer (4 papers, 2020 to 2022). An epithelial or non-epithelial malignant neoplasm that arises from the liver. "In liver cancer, the inhibition of PIM2 decreases cell proliferation by modulating the cell cycle." (PMID 34511042, 2021). "Moreover, a decrease in PIM2 levels inhibits cell proliferation in liver cancer by modulating the cell cycle." (PMID 34511042, 2021).